FGL2 (fibrinogen like 2)
Diseases named in the same sentence as FGL2 in open-access papers (continued):
Sharing a sentence is not in itself a finding about the gene and the disease.
breast cancer (7 papers, 2020 to 2024). A primary or metastatic malignant neoplasm involving the breast. "On the other hand, others have found that high expression of FGL2 is associated with favourable survival of patients with lung adenocarcinoma or breast cancer." (PMID 35029030, 2022). "The low expression level of FGL2 is associated with a poor prognosis in patients with breast cancer." (PMID 35602471, 2022). "Interestingly, FGL2 was also identified as a protective prognostic biomarker in breast cancer, and high FGL2 expression was positively associated with antitumor immune cell infiltration." (PMID 38903931, 2024). "The expression level of FGL2 in breast cancer cells was significantly lower than that in adjacent normal tissues." (PMID 35602471, 2022). "In addition, the expression level of FGL2 is positively correlated with the infiltration of breast cancer cells, especially those with high anti-tumor activity." (PMID 35602471, 2022). "FGL2 is a membrane-bound or secreted protein expressed by macrophages, T cells, and tumor cells that has coagulation activity and immunosuppressive functions; it was found to promote mammary tumor progression by enhancing tumor angiogenesis or inducing epithelial-to-mesenchymal transition." (PMID 33488671, 2020).
lung adenocarcinoma (7 papers, 2020 to 2024). A carcinoma that arises from the lung and is characterized by the presence of malignant glandular epithelial cells. "FGL2 has previously been shown to be positively correlated with macrophage infiltration in lung adenocarcinoma and CD8-positive T cell activation, and is associated with a better prognosis." (PMID 36969247, 2023). "The TIMER database was used to discover the association between the immune status and FGL2 expression in lung adenocarcinoma." (PMID 32206449, 2020). "Thus, we propose that FGL2, which is positively associated with enhanced antitumor activities mediated by T cells, is a beneficial marker for lung adenocarcinoma treatment outcomes." (PMID 32206449, 2020). "Thus, we propose that high FGL2 expression, which is positively associated with enhanced antitumor activities mediated by T cells, is a beneficial marker for lung adenocarcinoma treatment outcomes." (PMID 32206449, 2020). "We utilized the GEPIA, PrognoScan and Kaplan-Meier plotter databases to analyze the relationship between FGL2 expression and the survival of lung adenocarcinoma patients." (PMID 32206449, 2020). "Then, we investigated the potential roles of FGL2 in lung adenocarcinoma with the TIMER database and functional enrichment analyses." (PMID 32206449, 2020). "Second, we analyzed the relationship of the FGL2 level and the prognostic survival of lung adenocarcinoma patients with three bioinformatics datasets." (PMID 32206449, 2020). "We found that FGL2 expression was significantly lower in lung adenocarcinoma tissue than in adjacent normal tissue." (PMID 32206449, 2020). "In this study, we systematically investigated the expression profile and potential functions of FGL2 in lung adenocarcinoma." (PMID 32206449, 2020). "Data obtained from the TCGA dataset and the Oncomine database indicated that FGL2 expression was significantly lower in lung adenocarcinoma tissue than in adjacent normal tissue." (PMID 32206449, 2020). "Related data were downloaded from the bioinformatics database TCGA Data Portal and used to compare the mRNA expression level of FGL2 in lung adenocarcinoma and normal adjacent tissues." (PMID 32206449, 2020). "A high FGL2 mRNA level was correlated with better prognostic outcomes of lung adenocarcinoma, including overall survival and progression-free survival." (PMID 32206449, 2020). "Functional enrichment analyses, including Gene Ontology (GO), Kyoto Encyclopedia of Genes and Genomes (KEGG) pathway and GSEA, were used to explore the potential functions of FGL2 in lung adenocarcinoma development." (PMID 32206449, 2020). "We used three databases (PrognoScan, GEPIA, Kaplan–Meier plotter) to analyze the prognostic value of FGL2 in lung adenocarcinoma." (PMID 32206449, 2020). "A high expression level of FGL2 was correlated with better prognostic outcomes of lung adenocarcinoma patients." (PMID 32206449, 2020). "To validate the relationship between FGL2 expression and immune cell infiltration, we also investigated the correlation between the immune marker sets of immune cells and FGL2 expression in lung adenocarcinoma with the TIMER and GEPIA databases." (PMID 32206449, 2020). "We infer that FGL2 affects the KEAP1 effect by influencing immune status in tumor environment of lung adenocarcinoma." (PMID 32206449, 2020). "High FGL2 mRNA expression was correlated with better prognostic outcomes of lung adenocarcinoma patients, including overall survival and progression-free survival." (PMID 32206449, 2020). "FGL2 expression was positively correlated with immune cell infiltration and immune marker sets in lung adenocarcinoma." (PMID 32206449, 2020). "Correlation between immune marker sets of immune cells and FGL2 expression in lung adenocarcinoma based data from GEPIA database." (PMID 32206449, 2020). "A high expression level of FGL2 was correlated with better prognostic outcomes of lung adenocarcinoma patients, including overall survival and progression-free survival." (PMID 32206449, 2020).
lung adenocarcinoma (continued). "We infer that FGL2 affect KRAS by influencing immune status in tumor environment of lung adenocarcinoma." (PMID 32206449, 2020). "Data downloaded from the TCGA dataset and PNAS were used to compare the FGL2 expression levels between lung adenocarcinoma and adjacent normal tissues." (PMID 32206449, 2020). "We found that FGL2 expression was significantly lower in lung adenocarcinoma tissue compared with adjacent normal tissue." (PMID 32206449, 2020). "The results showed that the mean FPKM value of FGL2 in lung adenocarcinoma was 3.266, which was significantly lower than that in normal adjacent tissue (3.958, P < 0.001)." (PMID 32206449, 2020). "In this study, we used bioinformatic analysis to discover the potential roles of FGL2 in lung adenocarcinoma." (PMID 32206449, 2020). "In the PrognoScan database, an analysis of the cohort GSE13213 showed that a high FGL2 mRNA level was related to better overall survival in lung adenocarcinoma (OS HR = 0.68, 95% CI = 0.48 to 0.96, Cox P = 0.029471)." (PMID 32206449, 2020). "In this study, we explored the expression profile and potential effects of FGL2 in lung adenocarcinoma." (PMID 32206449, 2020). "Then, we explored the correlation between FGL2 expression and the immune status in the tumor microenvironment of lung adenocarcinoma." (PMID 32206449, 2020). "So, we infer that FGL2 exert synergic effects with STK11 to enhance the cytotoxic T lymphocytes activities in tumor environment of lung adenocarcinoma." (PMID 32206449, 2020). "In the future studies, in vivo and in vitro experiments will carry out to demonstrate the role of FGL2 in modulating the T cell-mediated immune response in lung adenocarcinoma." (PMID 32206449, 2020). "Microarray data from PNAS and the GEO also showed that the FGL2 mRNA expression level was lower in lung adenocarcinoma tissue than in normal adjacent tissue." (PMID 32206449, 2020). "We used the TCGA and Oncomine datasets to compare the FGL2 expression levels between lung adenocarcinoma and adjacent normal tissues." (PMID 32206449, 2020). "First, we evaluated the expression of FGL2 in lung adenocarcinoma tissue and adjacent normal tissue." (PMID 32206449, 2020). "We used the TIMER database to explore the correlation between immune cell infiltration and FGL2 expression in lung adenocarcinoma." (PMID 32206449, 2020). "Three bioinformatics databases, including GEPIA, PrognoScan and Kaplan–Meier plotter, were adopted to analyze the relationship of FGL2 expression and the survival of lung adenocarcinoma patients." (PMID 32206449, 2020). "Correlation between immune marker sets of immune cells and FGL2 expression in lung adenocarcinoma based data from TIMER database." (PMID 32206449, 2020). "Similarly, FGL2 exerted antitumor effects in lung adenocarcinoma by heightening immune cell infiltration." (PMID 38903931, 2024). "However, another study found that the expression level of FGL2 correlated with better prognostic outcomes of lung adenocarcinoma." (PMID 35860577, 2022). "FGL2 probably serves as a beneficial marker for the treatment of lung adenocarcinoma." (PMID 33867830, 2021). "Finally, we performed functional enrichment analysis to explore the biological functions of FGL2 in lung adenocarcinoma." (PMID 32206449, 2020). "FGL2 might affect other genes functions by influencing immune status in tumor environment of lung adenocarcinoma." (PMID 32206449, 2020). "In this study, we systematically explored the potential roles of FGL2 in lung adenocarcinoma." (PMID 32206449, 2020). "Owning to the B cells functions in antitumor immunity is dualistic, FGL2 might possessed poor or moderate correlation with B cells in the tumor microenvironment of lung adenocarcinoma." (PMID 32206449, 2020). "We also conducted GSEA to explore the biological functions of FGL2 in lung adenocarcinoma." (PMID 32206449, 2020). "Then, we investigated the potential mechanism of FGL2 in lung adenocarcinoma." (PMID 32206449, 2020).
lung adenocarcinoma (continued). "So, FGL2 might affect NF1 function by influencing immune status in tumor environment of lung adenocarcinoma." (PMID 32206449, 2020). "In the Kaplan–Meier plotter database, high FGL2 mRNA expression was correlated with better overall survival and progression-free survival in lung adenocarcinoma patients (OS HR = 0.64, 95% CI = 0.50 to 0.81, log-rank P = 0.00027; FP HR = 0.57, 95% CI = 0.41 to 0.79, log-rank P = 0.00061)." (PMID 32206449, 2020). "This implied that FGL2 might be a beneficial biomarker of lung adenocarcinoma." (PMID 32206449, 2020). "FGL2 was positively correlated with the infiltration of immune cells, including dendritic cells, CD8+ T cells, macrophages, B cells, and CD4+ T cells, in lung adenocarcinoma." (PMID 32206449, 2020). "In our study, we demonstrated FGL2 was positively correlated with T cells, especially CD8+T cells activation in the tumor microenvironment of lung adenocarcinoma patients." (PMID 32206449, 2020). "FGL2 was positively correlated with the infiltration of immune cells, including CD8+ T cells, CD4+ T cells, macrophages, B cells and dendritic cells, in lung adenocarcinoma." (PMID 32206449, 2020). "In our study, we found that FGL2 expression was positively corelated to the infiltration of CD4+ T cells, CD8+ T cells, macrophages, B cells and DCs in lung adenocarcinoma." (PMID 32206449, 2020). "This might explain the reason that correlation between FGL2 and CD4+ T cells was poor and moderate in lung adenocarcinoma." (PMID 32206449, 2020). "The results showed that FGL2 has not possessed strong correlation with B cells in the tumor microenvironment of lung adenocarcinoma." (PMID 32206449, 2020).
Sepsis (7 papers, 2018 to 2024). Sepsis is defined as life-threatening organ dysfunction caused by a dysregulated host response to infection. "Our previous study showed that Fgl2 deficiency delayed inflammation resolution 10, here we found that dabigatran did not improve the sepsis survival in Fgl2 knockout mice, indicating that Fgl2 was required for dabigatran-improved sepsis resolution." (PMID 33754059, 2021). "Five genes (NKG7, SPTA1, FGL2, RGS2, and IFI27) have been proved to be potential biomarkers for sepsis-induced ARDS and exert crucial roles in the occurrence and development of sepsis." (PMID 36299685, 2022). "We recently highlighted a link between fibrinogen-like protein 2 (Fgl2) and a specialized pro-resolving mediator (SPM)-n-3 docosapentaenoic acid-derived resolvin D5 (RvD5n-3 DPA) in sepsis." (PMID 33754059, 2021). "In summary, our study identified five key genes including NKG7, SPTA1, FGL2, RGS2, and IFI27, which were closely related to the sepsis-induced ARDS development." (PMID 34393665, 2021). "In a study on sepsis, patients who did not survive had decreased plasma levels of soluble FGL2 and upregulated membrane-bound FGL2 on leukocytes compared to patients who survived." (PMID 36671474, 2022). "It is also indicated in the previous research that FGL2 mediates regulatory T cells and MDSCs suppressor function through inducing ROS production and promotes the activation of the XBP1 pathway and cholesterol synthesis in sepsis, which characterized by immune paralysis." (PMID 39629005, 2024). "Furthermore, five genes including NKG7, SPTA1, FGL2, RGS2 and IFI27 exhibited significant differences between the sepsis-induced ARDS samples and the samples with sepsis alone in two datasets, suggesting that these five genes might be key genes that led to sepsis patients complicated with ARDS." (PMID 34393665, 2021). "Moreover, five genes including NKG7, SPTA1, FGL2, RGS2, and IFI27 exhibited notable difference between the sepsis-induced ARDS group and the control group with sepsis alone in two datasets, suggesting that these five genes might be key genes that led to sepsis patients complicated with ARDS." (PMID 34393665, 2021).
COVID-19 (6 papers, 2021 to 2025). A disease caused by infection with severe acute respiratory syndrome coronavirus 2. "Both chronic LCMV infection in mice and COVID-19 in humans resulted in a significant increase in plasma Fgl2." (PMID 40197366, 2025). "Similarly, plasma Fgl2 was directly proportional to CD8+ T cell lymphopenia in patients with COVID-19." (PMID 40197366, 2025). "Fgl2 was also upregulated in CD8+ T cells from patients with COVID-19 versus healthy controls." (PMID 40197366, 2025). "The genes most significantly upregulated in the lungs of COVID-19 patients are SERPINS E1, F1, G1 that encode for antiplasmin, tissue plasminogen activator inhibitor 1, and C1-esterase inhibitor, as well as the prothrombinase FGL2 (fibrinogen like protein 2)." (PMID 34585129, 2021). "FGL2 is characterized by complexity and multifunctionality and is involved in cardiovascular diseases and conditions, including the progression of pulmonary hypertension, COVID-19-generated thrombosis, autoimmune myocarditis, and dilated cardiomyopathy in mice, and in an AF porcine model." (PMID 37893006, 2023).
autoimmune glomerulonephritis (5 papers, 2015 to 2022). An autoimmune form of glomerulonephritis (disease). "It is also known to have immunosuppressive effects as evidenced by autoimmune glomerulonephritis in mice deficient in FGL2." (PMID 33375291, 2020). "Like FGL2-deficient mice, FcγRIIB-deficient mice also develop autoimmune glomerulonephritis." (PMID 33375291, 2020). "Mice deficient in FGL2 develop autoimmune glomerulonephritis." (PMID 25763980, 2015). "Shalev and colleagues found that mice with a targeted deletion of FGL2 as well as wild-type mice reconstituted with FGL2−/− bone marrow developed autoimmune glomerulonephritis with increasing age." (PMID 36671474, 2022). "Subsequently, FGL2 has been implicated as a repressor of T-cell activation both in the ability of recombinant FGL2 to block graft rejection and in the context of Fgl2 knockout mice developing autoimmune glomerulonephritis." (PMID 26362649, 2015).
Cirrhosis (5 papers, 2014 to 2024). A chronic disorder of the liver in which liver tissue becomes scarred and is partially replaced by regenerative nodules and fibrotic tissue resulting in loss of liver function. "Hoang and his colleagues discovered that FGL2 levels were remarkably increased in patients with cirrhosis and HCC compared to controls." (PMID 34879827, 2021). "At the same time, the close relationship between the FCGR3A and FGL2 expression and immune cells might be a key factor in the development of cirrhosis of the liver." (PMID 39629005, 2024). "Therefore, FGL2 plays a vital role during acute immune responses against HBV and HCV and is involved in the pathogenesis of the infections, particularly in the development of HBV-related cirrhosis." (PMID 30419833, 2018). "In this study, we demonstrate that patients with cirrhosis express significantly higher levels of FGL2 compared with patients without cirrhosis, independently of whether they have HCC, suggesting that the presence of activated HSCs may account for the high levels of FGL2." (PMID 25298849, 2014). "Plasma FGL2 levels are higher in patients with HCV-related LC compared to those without cirrhosis and correlated with more severe cirrhosis." (PMID 30419833, 2018).
clear cell renal cell carcinoma (5 papers, 2017 to 2022). "Furthermore, it was revealed that overexpression of FGL2 is significantly associated with poor prognosis in patients with clear cell renal cell carcinoma." (PMID 32596316, 2020). "This study evaluated the clinical significance of FGL2 in patients with clear cell renal cell carcinoma (ccRCC)." (PMID 28978925, 2017). "Importantly, FGL2 is over-expressed in colorectal carcinoma (CRC) and clear cell renal cell carcinoma (ccRCC) tumors compared to non-tumor tissues, and the expression levels are associated with cell proliferation and invasion in vitro and with CRC progression and metastasis in vivo." (PMID 30419833, 2018).
fulminant viral hepatitis (5 papers, 2011 to 2020). Fulminant viral hepatitis is a rapid and severe impairment of liver functions (acute liver failure) with hepatic encephalopathy developing less than 8 weeks after the onset of jaundice, secondary to viral hepatitis mainly due to HBV, but also to HAV. "MHV strain-3 (MHV-3) causes a viral fulminant hepatitis that results in production of fibrinogen-like protein-2 (FGL2), a monocyte/macrophage-specific procoagulant." (PMID 33149733, 2020). "The CD3+CD4−CD8− double-negative T cells appear to contribute to the pathogenesis and clinical outcome of MHV-3-induced fulminant viral hepatitis via the immunoactivity of FGL2 in a mouse model." (PMID 30419833, 2018). "Expression of FGL2 was associated with susceptibility to murine hepatitis virus strain 3 (MHV-3) infection in vivo, and the FGL2 gene has been suggested as a potential target for treatment of fulminant viral hepatitis." (PMID 30419833, 2018).
inflammatory bowel disease (5 papers, 2018 to 2025). A spectrum of small and large bowel inflammatory diseases of unknown etiology. "Elevated Fgl2 levels are observed in patients with inflammatory bowel disease (IBD), but little is known about its functional significance." (PMID 29441068, 2018). "Previous studies have shown that FGL2 plays an important role in inflammatory diseases such as severe viral hepatitis, rheumatoid arthritis, chronic obstructive pulmonary disease (COPD),and inflammatory bowel disease (IBD)." (PMID 36313679, 2022).